NES (nestin)
Diseases named in the same sentence as NES in open-access papers (continued):
Sharing a sentence is not in itself a finding about the gene and the disease.
cancer (continued). "The neurospheres showed characteristics consistent with GICs: namely, neurosphere formation, expression of neural and/or cancer stem cell markers CD133 and Nestin and expression of core stemness factors Sox2, OCT4 and Nanog." (PMID 27119230, 2016). "Nestin regulates prostate cancer cell invasion, EMT-related factors in pancreatic adenocarcinoma, and drug resistance in other cancers." (PMID 27412382, 2016). "Of which, the cancer stem cell markers such as SRY (sex determining region Y)-box 2 (SOX2) and Nestin have gotten researchers interested." (PMID 27150062, 2016). "Downstream signaling of nestin [cyclin-dependent kinase 5 (CDK5) and Ras-related C3 botulinum toxin substrate 1 (Rac1)] functions in cancer to modulate cellular behaviors." (PMID 25371063, 2015). "Appropriate amount of nestin enhances CDK5 function to suppress Rac1 and excessive nestin/CDK5 participates in multiple oncogenic pathways to promote cancer invasiveness." (PMID 25371063, 2015). "The expression of cancer SLC markers CD133 and nestin was detected using immunocytochemistry in order to identify U87 SLCs." (PMID 25760394, 2015). "The expression of NANOG, OCT4, Sox, NESTIN and CD44 has been observed in human prostate ADC cells, which suggests the importance of cancer stem and progenitor cells in prostate carcinogenesis." (PMID 25120646, 2014). "The co-culture of cancer cells and PSCs induced an alteration in expression of the CSC-related genes: nestin, ABCG2 and LIN28 in the cancer cells, indicating a CSC-like phenotype." (PMID 25337831, 2014). "The results of this study indicated that indirect co-culture of pancreatic cancer cells and PSCs enhanced the spheroid-forming ability of the cancer cells and induced expression of the PCSC-related genes ABCG2 and Nestin." (PMID 24325450, 2013). "We show that CD44 is expressed in nearly all cancer cells in our cell lines and CD133 is expressed in both Oct4 and nestin cell populations." (PMID 24160469, 2013). "More interestingly, in several samples, we found that cancer cells with high expression of ESCs-related marker SOX2, OCT4 and Nanog, particularly SOX2, were surrounded by Nestin positive-endothelium." (PMID 23424657, 2013). "Most recently, it has been reported that PSCs increase the stem cell phenotype of cancer cells, as assessed by increased expression of stem cell markers such as nestin, ABCG2, and LIN28 in cancer cells upon co-culture with PSCs." (PMID 22973234, 2012). "Co-expression of nestin and the CD133 surface molecule is considered to be a marker for cancer stem cells in neurogenic tumors." (PMID 18925963, 2008). "Hypofractionated carcinomas lack the polyblastic component of thyroblastoma and are negative for neuroepithelial labelling by Syn and Nestin." (PMID 40007992, 2025). "Additionally, to evaluate the effect of HNF4A on the stemness of the spheroids, we screened for expression of cancer stem cell markers, including CD24, CD44, NESTIN, OCT4, and SOX2." (PMID 39165427, 2024). "For example nestin, a class VI intermediate filament protein found in the cell cytoplasm, and a CSC marker; and fibroblast growth factor receptor 1 (FGFR1), a tyrosine kinase receptor which enhances cancer cell proliferation and migration." (PMID 33637089, 2021). "However, genes associated with cell differentiation (EPCAM, CK8, CK18, and FOXA2), EMT (SNAI1, FOSL1, and ID1), and cancer stem cells (CD44, CD133, ETV1, MALAT1, NEAT1, and NESTIN) displayed a more varied response compared to 2D cells." (PMID 33356003, 2021). "Nestin has been shown to be strongly correlated with lower cancer patient survival, while some researchers hold the opposing view that there is no connection between Nestin expression and poor prognosis in GBM." (PMID 34307170, 2021). "In addition, CPZ was able to downregulate the expression of OCT 3/4, SOX2, NANOG, Nestin, OLIG2 and ALDH1A3, universal cancer stem cells genes for GBM." (PMID 33718225, 2021).
cancer (continued). "Finally, cancer stem cell markers CD44, CD133, and NESTIN displayed a similar averaged RNA expression to 2D grown cells." (PMID 33356003, 2021). "In order to better define the effects on CSCs and provide a solid platform for future repositioning of DSF-Cu++, cellular expression of ALDH and of other markers of cancer cell stemness (CD133 and Nestin) were included in our analysis using both in vivo and in vitro techniques." (PMID 34731160, 2021). "The existence of CSCs in NB has been associated with malignancy, resistance to chemotherapy and recurrence, as in chemo- and/or radiation-resistant NB cancer stem-like cells an increased expression of the stem cell markers CD133, SOX2, ALDH1, Nestin, OCT4, and NANOG was observed." (PMID 32158431, 2020). "Activation of the mitochondrial membrane potential can be detected by comparing tetramethylrodamine ester (TMRE) staining between cancer cells and human pancreatic nestin-expressing (HPNE) cells under normal culture conditions (normoxia and high glucose)." (PMID 32882923, 2020). "The spheres could be expanded and maintained as spheroids through many passages and expressed cancer stem cell marker, CD133 and nestin." (PMID 31035344, 2019). "Furthermore, we found that Nestin was related to KRAS activation and gene expression patterns thought to reflect cancer stemness, such as activation of Wnt/β-Catenin related pathways and retinol metabolism." (PMID 28439082, 2017). "These cells express cancer stem cell and neural stem cell markers CD133 and Nestin." (PMID 28228863, 2017). "Of note, both nestin and CD133 have been used to detect and purify cancer stem cells in NB31." (PMID 29203817, 2017). "With progress of cancer biology, a number of genes have been investigated for predicting prognosis of NSCLC, such as cancer stem cell markers SRY (sex determining region Y)-box 2 (SOX2) and Nestin." (PMID 27150062, 2016). "Expression of further cancer stem cell markers like CD133 and Nestin was unaffected." (PMID 27203385, 2016). "Immunofluorescence analysis demonstrated the presence of de-differentiated NESTIN+ and SOX2+ cancer cell populations as well as oligodendrocytes (O4), astrocytes (GFAP) and neurons (TUJ-1) confirming the in vivo differentiation potential of the generated GTIC-like cells." (PMID 26899176, 2016). "c-MYC, ABCG2, NESTIN and OCT4 have important role in cancer progression." (PMID 27054115, 2016). "Suppression of the nestin/CDK5 complex reduces proliferation, migration and metastasis in cancer." (PMID 25371063, 2015). "Firstly, this meta-analysis was based on pooled positive or high nestin data; thus, we were only able to address the relationship between positive/high nestin and cancer stage, and not individual positive or high-nestin values." (PMID 26015397, 2015). "After applying specific inclusion criteria, we chose seven articles relating to nestin expression and cancer stage, which included a total of 223 positive/high nestin cases and 460 negative/low case-free controls." (PMID 26015397, 2015). "Ultimately, seven studies on nestin and cancer staging that included a total of 223 positive/high nestin cases and 460 negative/low case-free controls were deemed eligible for the final analysis." (PMID 26015397, 2015). "Moreover, the CD133+ cells showed characteristics consistent with CSC, namely neurospheres formation, expression of neural/cancer stem cell markers (CD133, Nestin, SOX-2) and differentiation marker (GFAP)." (PMID 24978848, 2014). "Significantly poorer rates of cancer-specific survival and overall survival were seen in the nestin-positive group compared with the nestin-negative group (p = 0.0051 and 0.0148, respectively)." (PMID 24785714, 2014). "The role of the BMP signaling cascade regulating the expression of Id proteins and growth of cancer cells expressing Oct4 or nestin is not known." (PMID 24160469, 2013).
cancer (continued). "Oct4 and Nanog are exclusively expressed in embryonic stem cells, Nestin is expressed in pluripotent neural stem cells, while KLF4, c-myc, and genes of Notch, SHH, and WNT pathways are expressed in TICs of a variety of cancers." (PMID 23185379, 2012). "The expression of OCT4, NANOG, NESTIN, and BRY was tested in cancer cell lines also." (PMID 21785609, 2011). "In both cancer cell-lines, KU174 demonstrated a dose-dependent reduction in Hsp (Hsc70 and Hsp27), HSF-1 and client proteins (survivin Akt, Her2, nestin, CXCR4 and caspase-3) whereas, a minimal effect was seen on these proteins in normal RPTEC cells (data not shown)." (PMID 22039910, 2011). "Both pseudotyped lentiviral vectors transduced cancer stem-like cells characterized by their CD133-, nestin- and SOX2-expression, the ability to form spheroids in neural stem cell medium and to express astrocytic and neuronal differentiation markers under serum conditions." (PMID 19617915, 2009). "We previously showed that nestin inhibits the binding of vimentin’s tail domain to actin filaments (AFs) by steric hindrance through its large nestin tail domain (NTD), thereby increasing three-dimensional cytoskeleton network mobility, enhancing cell flexibility, and promoting cancer progression." (PMID 39851565, 2025). "Additionally, we evaluated the expression of some cancer‐related proteins in ex vivo tumors from both groups, including proliferation (Ki‐67 and Cyclin D1), anti‐apoptotic (BCL2), and stemness (NESTIN and SOX2) markers, collected at distinct time points according to animal survival times." (PMID 34919784, 2022). "However, since the inhibition of apoptosis by nestin has not been observed in all types of cancer, more research is needed." (PMID 34943921, 2021). "Instead, malignant tumors have shown different grades of nestin immune expression and, independent of its degree, it could be helpful to assess the malignant character of a lesion in small biopsies." (PMID 33805026, 2021). "Furthermore, we aimed in the present study to evaluate the expression of nestin, NGFR, Sox10, FZD6 and PROM1 cancer stem cell markers and angiogenic factors in UM and to better understand the relationships between the detected markers and vasculogenic mimicry patterns." (PMID 33255843, 2020). "Overlapping molecules in two groups included up-regulated transforming growth factor beta induced (TGFBI) and Nestin (NES); and down-regulated synuclein alpha (SNCA) and heat shock protein family A member 12A (HSPA12A), which have demonstrated roles in GBM and/or other cancers." (PMID 29228611, 2017). "We hypothesized that nestin/CDK5/Rac1 signaling behaves different in early and advanced cancer." (PMID 25371063, 2015). "Of the remaining 14 studies, seven did not focus on nestin and cancer staging." (PMID 26015397, 2015). "In addition, another critical role of PSCs in PDAC progression has been documented to be associated with the pancreatic cancer-stem-cell through enhancing the spheroid-forming ability of cancer cells and inducing the expression of cancer stem cell-related genes ABCG2, Nestin, and LIN28." (PMID 24587996, 2014). "In addition, patients without lymph node involvement and without nestin expression showed prolonged progression-free survival and cancer-specific survival (data not shown)." (PMID 24785714, 2014). "However, the immunohistochemical expression of CD133 and NESTIN was extremely weak or absent in the cancer cells of prostate ADC and those of non-cancerous cells." (PMID 25120646, 2014). "Therefore, GBM cancer cells could shift cancer cells from the proliferation state to hibernation state through autophagy as a survival function, followed by enhancement of CD133/CD44/Nestin/SOX2 as GSC markers to support the stochastic model." (PMID 34069945, 2021). "Immunofluorescence staining for nestin but not GFAP and β-tubulin was observed in the cancer stem cells, which contrasts with the results observed in cancer cells." (PMID 28955297, 2017).
cancer (continued). "GSCs lacking A3AR exhibited common properties of Cancer Stem Cells forming neurospheres clusters expressing the Stem Cells markers (CD44, CD133 and Nestin)." (PMID 27634913, 2016). "Regarding the patients with negative nestin expression, the activation of NOTCH, TGF-β1 or PDGFR pathways could induce cancer metastasis." (PMID 25371063, 2015). "Among patients with negative nestin expression, the activation of Notch, TGF-β1 or PDGFR pathways and suppression of PTEN may induce cancer metastasis." (PMID 25371063, 2015).
infection (31 papers, 2009 to 2026). The state of being infected such as from the introduction of a foreign agent such as serum, vaccine, antigenic substance or organism. "GFP driven by the synapsin promoter was included as an infection marker to visualize transduced neurons; Nestin is a marker for DIPG cells." (PMID 35311648, 2022). "Infection of Nestin-Cretg/+ MALT1FL/FL and LysMCretg/+ MALT1FL/FL mice yielded survival results comparable to those of wild-type littermates, excluding a role for MALT1 in neurons, astrocytes, oligodendrocytes, or myeloid cells." (PMID 29367251, 2018). "Three days after infection immunofluorescence experiments were performed to detect the viral cytotoxic protein NS-1 (red) and the neuroepithelial stem cell marker protein Nestin (green)." (PMID 27213425, 2016). "Bone marrow cells producing the intermediate filament nestin guide monocyte egress to the bloodstream in response to infection." (PMID 27586429, 2016). "In our study, cells that interfered with were not limited to nestin-immunoreactive stem cells, other stem cells or neuroblasts were also under affection, due to the extensive infection of lentiviruses." (PMID 27242411, 2016). "Bone marrow (BM) nestin+ cells cooperate with endothelial cells in directing monocyte egress to bloodstream in response to infections." (PMID 27586429, 2016). "The infection of aortic vascular smooth muscle cells with a lentivirus containing a shRNAmir directed against nestin significantly reduced protein expression and concomitantly attenuated basal DNA synthesis." (PMID 25139503, 2014). "We have previously shown that MCMV can establish productive infection in cells which express nestin." (PMID 21249143, 2011). "In Ntv-a mice, the nestin promoter directs infection to neural/glial progenitor cells, while in Gtv-a mice, the glial fibrillary acidic protein (GFAP) promoter directs infection mainly to astrocytes." (PMID 21949886, 2011). "The distribution of recent and matured virus protein appeared similar in nestin+ progenitor cells and in the three cell lineages, suggesting that progenitor cells and each cell lineage were equally susceptible to Timer-CVB3 infection upon initial infection." (PMID 24722773, 2014). "In addition, reduced expression of hNPCs stemness marker Nestin was observed throughout the infection time course." (PMID 25343994, 2014). "First, we demonstrated that brain-derived neurotrophic factor (BDNF), glial-derived neurotrophic factor (GDNF), neurotrophin-3 (NT3), and their combinations (GBN) could significantly inhibit WSN infection at the NESTIN+ NSCs level, especially BDNF and GBN in NP+ cells." (PMID 35910807, 2022). "Through co‐expression analysis of mCherry and Leydig cell progenitors markers, platelet‐derived growth factor receptor alpha (PDGFRα) and Nestin, we observed a dose‐dependent increase in AAVDJ infection efficiency in Leydig cell progenitors." (PMID 38817099, 2024). "Immunofluorescence staining and flow cytometry for Nestin, an NSC marker, showed that K-NSCs maintained the expression of Nestin, indicating that rAAV2-infected K-NSCs remained undifferentiated 1-week post infection." (PMID 37111381, 2023). "Similar to the Gbaflox/flox; nestin-Cre mouse, CBE-treated mice were more resistant to SVNI infection (hereafter referred to as CBE + SVNI mice) with undefined median survival compared to 6 days of the control." (PMID 32831144, 2020). "Mice specifically lacking MALT1 in myeloid cells (LysMCretg/+ MALT1FL/FL) or cells of neuroectodermal origin (neurons, astrocytes, or oligodendrocytes; Nestin-Cretg/+ MALT1FL/FL) were therefore also generated and analyzed in similar infection experiments." (PMID 29367251, 2018). "Upon infection with the reporter vector, the endogenous basal level expression of nestin was observed in human BM-derived MSCs without any treatment." (PMID 39125577, 2024).
infection (continued). "Whereas in BM‐EVs treated NS, except Mash1 and Nestin, all other marker expression was increased compared to only JEV‐infected group, suggesting BM‐EVs support the process of neurogenesis even in the infection scenario." (PMID 36479206, 2022). "We next investigated the kinetics of RNA levels of selected markers for neural progenitors (NES for nestin) and for markers of mature neurons (TUBB3 and RBFOX3 for β3-tubulin and NeuN, respectively) at 24 h, day 3 and 5 after infection, detected by quantitative RT-PCR." (PMID 33490061, 2020). "In contrast to control mice, which had a median survival of 7 days post infection (DPI) with SVNI, infected Gbaflox/flox; nestin-Cre mice had a longer lifespan with median survival of 14 days, similar to uninfected Gbaflox/flox; nestin-Cre mice (median of 11 days)." (PMID 32831144, 2020). "MV-infected CD46+/IFNγ-KO explants displayed significantly lower nestin expression compared to MV-infected CD46+ mice, which displayed no change with infection." (PMID 27178303, 2016). "Reduction of Nestin levels was not seen until 24 h.p.i, which is the time point SINV reached its highest infection rate, indicating that alteration in cell multipotency also correlated with virus replication." (PMID 25343994, 2014).
neurodegenerative disease (7 papers, 2016 to 2022). A disorder of the central nervous system characterized by gradual and progressive loss of neural tissue and neurologic function. "Loss of either Atg5 or Atg7 in neural cells under the control of the Nestin promoter (Nestin-Cre) were shown to cause neurodegenerative disease in mice." (PMID 32195258, 2020). "Considering the important function of Nestin in multiple organs and systems, there should be wider application of Nestin-targeted therapy in other degenerative diseases, which can be explored in future studies." (PMID 35821241, 2022). "In pre-clinical settings, previous work seems to have focused on immunofluorescence expressions of Nestin with few studies on its involvement in neurodegenerative diseases." (PMID 34572456, 2021). "In parallel, the mechanistic role and promising therapeutic value of Nestin+ cells is also under research in preclinical models of disease, especially neurodegenerative diseases and bone marrow malignancies." (PMID 29541793, 2018). "In addition to the current model already established, future improved in vivo models and detections tools to unravel the therapeutic applications of Nestin in different neurodegenerative diseases are of utmost importance." (PMID 34572456, 2021). "Hence, it is reasonable to hypothesize that bone marrow Nestin+ MSCs may provide a useful source for cell therapy in neurodegenerative diseases." (PMID 29541793, 2018).
adenocarcinoma (4 papers, 2013 to 2021). A common cancer characterized by the presence of malignant glandular cells. "Nestin inhibition by shRNA decreased proliferation, migration, invasion, and sphere formation in adenocarcinoma cells." (PMID 27018053, 2016). "Hematoxylin and Eosin staining demonstrated that the Oct4/GFP and Nestin/GFP tumors recapitulated adenocarcinomas of the lung but the degree of differentiation was different." (PMID 24160469, 2013). "In another study, nestin protein expression significantly correlated with tumor size and lymph node metastasis in NSCLC and also poor survival in patients with adenocarcinoma." (PMID 27018053, 2016).